NF2 (NF2, moesin-ezrin-radixin like (MERLIN) tumor suppressor)
Diseases named in the same sentence as NF2 in open-access papers (continued):
Sharing a sentence is not in itself a finding about the gene and the disease.
schwannoma (continued). "In NF2-related schwannomas, sporadic vestibular schwannomas and Schwannomatosis-related schwannomas, the NF2 gene is commonly found inactivated in both alleles, with a high percentage of mutations revealed by loss of heterozygosity (LOH)." (PMID 25739810, 2015). "Schwannomas are the most common neurofibromatosis type 2 (NF2)-associated tumors with significant phenotypic heterogeneity in patients." (PMID 24980480, 2014). "Secondly, sporadic schwannomas depend on the acquired somatic mutations in both alleles of the NF2 gene." (PMID 25012216, 2014). "The hallmark feature of NF2 is the bilateral occurrence of schwannomas at the eighth cranial nerve (vestibular schwannoma)." (PMID 25012216, 2014). "Merlin is encoded by neurofibromatosis type 2 (NF2) gene and mutations and deletions of merlin underlie NF2 familial cancer syndrome, characterized by development of schwannomas, meningiomas and ependymomas." (PMID 23565227, 2013). "The hallmark of NF2 is the formation of bilateral schwannomas in the vestibular branch of the auditory nerve." (PMID 24259290, 2013). "Eight of the schwannomas (50%) had NF2 sequence mutations detected by PCR/dHPLC, and 10 of the schwannomas (62%) had NF2 sequence mutations detected by the combined MLPA and PCR/dHPLC analysis." (PMID 23776562, 2013). "No exclusive clinicopathological similarities were found within schwannoma groups 1, 2-I and 2-II, even with the 3 NF2-associated samples distributed among all groups." (PMID 23354516, 2013). "The candidate driver was NF2, a gene whose loss-function mutation is known to cause human schwannomas." (PMID 24009526, 2013). "While NF2 inactivation has been linked to schwannomas and other tumors such as mesotheliomas, loss of NF2 expression appears to be infrequent in human glioblastoma, though it has been reported in up to one third of cases." (PMID 23308224, 2013). "The NF2 gene, a tumor suppressor located at 22q12 that encodes a protein termed merlin or schwannomin, is mutated in up to 66% of sporadic schwannomas." (PMID 23354516, 2013). "The presence of multiple schwannomas in a single patient suggests possible association with neurofibromatosis type 2 (NF2) or schwannomatosis." (PMID 22937797, 2012). "The NF2 gene is frequently mutated in NF2-related vestibular schwannomas, and mutations in this gene have also been found in sporadic unilateral schwannomas." (PMID 22295085, 2012). "The majority of schwannomas arise spontaneously and only 4% are associated with neurofibromatosis type 2 (NF2)." (PMID 22911524, 2012). "In humans, loss of NF2 function is linked to tumours of the central nervous system, particularly benign tumours such as schwannomas, although in mice loss of NF2 has been associated with a variety of malignant tumours." (PMID 22359511, 2012). "The loss of both wild-type copies of the NF2 tumor suppressor gene is common in the pathogenesis of both sporadic and NF2-related schwannomas." (PMID 22295085, 2012). "Loss on 22q was reported in 23% of sporadic schwannomas, in which case it was slightly more common in tumors associated to NF2 than those found in sporadic cases, but this difference was not significant." (PMID 22911524, 2012). "Certain schwannomas, especially the bilateral vestibular ones, are associated with neurofibromatosis type 2 (NF2) syndrome and hereditary NF2 gene mutations." (PMID 23320233, 2012). "Loss of heterozygosity, ie, gross deletion of the NF2 gene is a common feature found in the majority of sporadic schwannomas." (PMID 22911524, 2012). "The evidence very strongly suggests that all schwannomas are caused by changes in both gene copies and the consequent loss of NF2 protein function." (PMID 22911524, 2012). "At present, it seems that all sporadic schwannomas are caused by some kind of alteration of NF2 gene." (PMID 22911524, 2012). "Today, it is recognized that alterations of the NF2 gene are a causative event in the tumorigenesis of schwannomas." (PMID 22911524, 2012).
schwannoma (continued). "NF2-deficient Schwannoma cells display aberrant membrane ruffling and concomitant hyperactivation of Rac and Pak1." (PMID 21072183, 2010). "We present a case of a 51-year-old male with a pseudoglandular cellular schwannoma arising from the brachial plexus, which contains the expected molecular aberrations for a schwannoma (chromosome 22q loss encompassing the NF2 and LZTR1 genes) as well as a FUS::KLF17 rearrangement." (PMID 40878925, 2025). "In some cases, especially in pediatric patients, further genetic evaluation may be warranted to rule out syndromic associations such as neurofibromatosis type 2 (NF2), which is commonly associated with multiple nervous system tumors, including schwannomas." (PMID 40672023, 2025). "Although there is full agreement in the literature that schwannomas originate from a double random mutation—of which frameshift mutations are the most common—in 4% of cases these lesions are multiple and associated with NF2." (PMID 40722574, 2025). "In our current study, we purified sEVs from the culture medium of primary NF2-associated schwannoma cells and conducted a thorough proteomic analysis to investigate their potential roles in microenvironment modulation and tumor progression, as well as the underlying mechanisms involved." (PMID 41149489, 2025). "The autosomal dominant inherited tumour predisposition syndromes, schwannomatosis (collectively termed non-NF2-related SWN) and neurofibromatosis type-2 (NF2) (now designated as NF2-related schwannomatosis), predispose affected individuals to the development of schwannomas." (PMID 40794298, 2025). "According to statistics, more than half of sporadic schwannomas harbor inactivating NF2 mutations." (PMID 41300852, 2025). "However, the loss of the wild-type SMARCB1 allele is insufficient for schwannoma growth which appears to be dependent upon concomitant somatic NF2 PVs in patients with SMARCB1-related schwannomatosis according to the four-hit/three-step model of tumorigenesis." (PMID 40794298, 2025). "Accumulating evidence indicates that Schwann cell neoplastic transformation is driven by loss-of-function mutations in the NF2 tumor-suppressor gene, and schwannoma development is causally linked to loss of merlin expression, the growth-inhibitory protein encoded at 22q12.2." (PMID 41300852, 2025). "Next, we evaluated the impact of NF2-EVs on the proliferation of NF2-associated schwannoma cells." (PMID 41149489, 2025). "Two blue module genes that are essential to ECM, CAV1 and CAV2, were conserved in both hiPSC and mouse derived SCs and may be linked to NF2-associated vesicle trafficking as previously shown in schwannoma." (PMID 40585242, 2025). "Additionally, these vesicles significantly enhance the proliferative capacity of NF2-associated schwannoma cells." (PMID 41149489, 2025). "Finally, the fourth hit (third step) involves a tumour-specific pathogenic variant of the NF2 gene located in cis to the SMARCB1 germline PV that leads to biallelic NF2 inactivation driving schwannoma development." (PMID 40794298, 2025). "Additionally, the merlin protein, encoded by the NF2 gene, is a known tumor suppressor whose loss is associated with schwannoma development." (PMID 41278265, 2025). "In a total of 153 patients aged younger than 24 years with an isolated schwannoma, genetic testing indicated that 15 (9.8%) patients had a germline NF2 pathogenic variant, six patients (3.9%) had a germline SMARCB1 PV, and 10 patients (6.5%) had a germline LZTR1 PV." (PMID 40794298, 2025). "Therefore, NF2 mutations at the somatic level account for the tumorigenesis of over half of all sporadic meningiomas, ependymomas, and schwannomas." (PMID 39796693, 2024). "Inactivation of both alleles of the NF2 gene is observed in most schwannomas." (PMID 38800239, 2024).
schwannoma (continued). "Although several mouse models for NF1-associated neurofibromas and NF2-associated schwannomas have been developed and successfully used to explore tumor biology and evaluate promising therapies, PSC engineering offers the opportunity to generate humanized mouse models of these tumors." (PMID 38353122, 2024). "Finally, we demonstrate the efficacy of PAK and TEAD inhibitor combinations in several NF2-deficient Schwannoma cell lines." (PMID 39083549, 2024). "Our studies suggest that the ability of Nf2−/− SCs to variably enact distinct programs of ErbB ligand production and cytoskeletal polarity upon loss of axonally provided nutrients is a key intrinsic driver of schwannoma heterogeneity." (PMID 36944680, 2023). "While approximately 90% of schwannomas are sporadic, some presentations may have syndromic associations, such as neurofibromatosis type 2 (NF2) and schwannomatosis." (PMID 38082359, 2023). "NF2 can cause schwannomas in the entire central and peripheral nervous systems." (PMID 37813009, 2023). "The molecular mechanism of schwannomatosis shows different somatic point mutations in NF2 between schwannomas in the same person; linkage analysis in a number of families to exclude the NF2 locus on chromosome 22q confirmed the existence of the separate entity." (PMID 35361920, 2022). "The IC50 for CUDC907 is approximately 100-fold lower than AR42 in primary human VS and Nf2-deficient mouse schwannoma cells, which may be related to synergistic effects of CUDC907 on both PI3K and HDAC pathways." (PMID 35875610, 2022). "Furthermore, many sporadically affected individuals that do not have either LZTR1 or SMARCB1 germline pathogenic variants but meet schwannomatosis criteria, have mosaic NF2 with identical pathogenic variants in two separate schwannomas." (PMID 35361920, 2022). "Schwannomas are benign peripheral nerve sheath tumors that arise sporadically or in the context of inheritable tumor predisposition; i.e., neurofibromatosis type 2 (NF2) or schwannomatosis." (PMID 35986430, 2022). "In this regard, Merlin, a tumor suppressor protein encoded by the NF2 gene, has been shown to be altered in neurofibromatosis type 2, an inherited disease that predisposes the bearer to the development of tumors, essentially schwannomas." (PMID 36361889, 2022). "However, the high frequency of LoF LZTR1 variants in the general population suggests that LZTR1 variants confer a reduced risk of schwannomas compared to germline NF2 and SMARCB1 pathogenic variants, making classification of novel variants challenging." (PMID 35391499, 2022). "In NF2-associated schwannomas with the same median values, intraspinal tumors exhibited a higher and therefore better preoperative MRC score compared to upper extremity (p = 0.001) cases but lower and thus worse postoperative SRS scores compared to tumors located at the torso (p = 0.023)." (PMID 35771312, 2022). "Schwannomas of the vestibular branch of the eighth cranial nerves are the most common in patients with NF2 gene mutations, although these neoplasms may also arise on any other cranial nerve." (PMID 35053664, 2022). "As our study is the first to validate the effect and mechanism of a Chinese medicine formula in treating NF2-associated schwannoma, further pharmacological and pharmacokinetic studies will be needed to understand the mechanisms and biological efficacy of QDSJ to optimize this therapeutic strategy." (PMID 36059985, 2022). "Treatment of NF2-associated MN and schwannomas with rapamycin analogs was found to be cytostatic." (PMID 33273014, 2021). "A large study analyzed MEKi selumetinib, trametinib, PD0325901, MEK162, cobimetinib and refametinib in NF2-associated merlin-deficient schwannoma cells and mouse models and identified trametinib, PD0325901 and cobimetinib to be the most effective as well as uncovered resistance mechanisms." (PMID 33863389, 2021).
schwannoma (continued). "Interestingly, previous reports have implicated overexpression of epidermal growth factor receptor family tyrosine kinases EGFR and ERBB2/HER2 in NF2-associated schwannomas and MN." (PMID 33273014, 2021). "Red circles highlight a contralateral 2.0 × 1–cm schwannoma, the hallmark of NF2." (PMID 36285231, 2021). "The growth of schwannomas requires inactivation of both NF2 alleles." (PMID 34072574, 2021). "NF2-associated schwannomas are often present early in childhood or young adulthood and are often associated with neurologic deficits such as weakness or sensory loss, while schwannomatosis-associated lesions are more often diagnosed later in life and are more frequently associated with pain." (PMID 31161239, 2020). "Evaluation of NF2-associated tumors has been limited to date, but one study showed PD-L1 expression (> 5% of tumor cells) in a substantial subset of NF2-associated schwannomas, suggesting that this may be an interesting avenue for further clinical study." (PMID 31161239, 2020). "The second patient presented as a Grade III tumor and also had multiple concurrent schwannomas raising the possibility that the patient may have had an NF2 associated Grade III ependymoma." (PMID 32641156, 2020). "However, with the exception of NF2 mutations in human schwannoma (49-66%), very few Hippo pathway mutations have been found in human tumors." (PMID 32960816, 2020). "A subset of NF2-associated schwannomas may also harbor the SH3PXD2A-HTRA1 gene fusion that has been identified in sporadic schwannoma." (PMID 31161239, 2020). "In addition, the somatic copy number alterations (CNA) was potentially associated with spinal schwannoma, among which NF2 was found to be frequently deleted in schwannoma samples." (PMID 33193598, 2020). "Although Nf2 tumor suppressor gene-deficient Schwann cells are the primary tumorigenic element and principle focus of current research efforts, evidence is accumulating regarding the contributory roles of other cell types in schwannoma pathology." (PMID 32616891, 2020). "These lesions may show loss of NF2 gene function and are hypothesized to represent precursor lesions to schwannomas." (PMID 31161239, 2020). "About 60% of the sporadic unilateral schwannomas have mutations in the NF2 gene." (PMID 32244314, 2020). "Schwannomas are typically benign slow-growing tumors characterized by a well-circumscribed population of spindled cells, though NF2-associated schwannomas may exhibit a variety of unusual features." (PMID 31161239, 2020). "However, instead of constitutional (germline) NF2 mutations, independent somatic mutations affecting both NF2 alleles are frequently found in schwannomas of patients with schwannomatosis." (PMID 27921248, 2017). "However, copy-number neutral LOH mediated by mitotic recombination is relatively frequent, observed in 19% of NF2-associated schwannomas and in 6% of sporadic schwannomas." (PMID 27921248, 2017). "In schwannomas considered as ‘one-hit’ tumours, the methylation of the promoter-associated CpG island may represent the event secondary to the inactivation of the NF2 gene." (PMID 28710469, 2017). "By inducing Smarcb1 loss at later developmental stage in the Schwann cell lineage, in addition to biallelic Nf2 gene inactivation, we generated the first mouse model developing schwannomas with the same underlying gene mutations found in schwannomatosis patients." (PMID 28824165, 2017). "Thus, ponatinib's lack of in vitro selectivity is not a cause for concern for in vivo studies and its potential as a therapeutic for NF2-associated schwannomas." (PMID 28427224, 2017). "LOH of large parts of 22q is observed in 67% of NF2-associated and 56% of sporadic schwannomas." (PMID 27921248, 2017). "Similar to SMARCB1-related schwannomas, different additional somatic mutations in NF2 were identified in schwannomas from these patients, thus supporting the 4-hit/3-step hypothesis." (PMID 28824165, 2017).
schwannoma (continued). "Nonetheless, it appears unresolved whether inactivation of both the Nf2 alleles in Schwann cells is a prerequisite for schwannoma development." (PMID 27236462, 2016). "Indeed, knockdown of MLK3 is sufficient to block JNK and ERK activation in a human schwannoma cell line bearing an NF2 loss-of–function mutation and, as a consequence, suppresses proliferation of these cells." (PMID 27213454, 2016). "We therefore set out to determine whether MET inhibition would be beneficial in a model of NF2-associated schwannoma." (PMID 27363027, 2016). "Schwannomas are benign Schwann cell-derived nerve sheath tumors that can occur either sporadically—in association with genetic syndromes such as schwannomatosis or neurofibromatosis type 2 (NF2)—or as a result of therapeutic irradiation." (PMID 27236462, 2016). "Schwannomas are predominantly benign nerve sheath neoplasms caused by Nf2 gene inactivation." (PMID 27236462, 2016). "Accordingly, two independent NF2 mutations, one in each schwannoma, were identified as second hits." (PMID 25739810, 2015). "A link between PDGFR expression and NF2 loss has been demonstrated in human schwannoma." (PMID 26418719, 2015). "An exhaustive molecular genetic analysis was performed in two schwannomas of the patient to identify mutations in the NF2 and SMARCB1 genes, including cDNA and DNA sequencing, MLPA, microsatellite multiplex PCR and SNP-array analyses, to clarify the molecular diagnostics." (PMID 25739810, 2015). "Furthermore, NF2 was also shown to inhibit PI3K activity by binding to PI3K enhancer-L (PIKE-L), which disrupts binding of PIKE-L to PI3K10 and loss of NF2 in schwannoma was shown to sensitize to PI3K inhibitors." (PMID 25950487, 2015). "Schwannomas with specific molecular characteristics, such as gene mutations of NF2 and/or LOH of 22q region, may present a different miRNA expression pattern when compared to unaltered schwannomas." (PMID 23776562, 2013). "We speculate that SIRT2 pharmacological inhibition may have some therapeutic value for NF2-associated schwannomas by promoting necrosis." (PMID 24259290, 2013). "Moreover, the same study reported difference in NF2 LOHs between vestibular and spinal schwannomas and the association of higher proliferative index to the schwannomas showing LOH." (PMID 22911524, 2012). "An initial investigation into the epigenetic landscape of NF2-associated schwannomas focused on promoter methylation, revealing that NF2 gene silencing through promoter hypermethylation may occur in a limited subset of tumours, indicating a rare yet potentially significant mechanism." (PMID 40843672, 2025). "Thus, loss of NF2 gene function is a crucial event initiating tumorigenesis in most schwannomas." (PMID 40794298, 2025). "Indeed, loss-of-function of NF2 appears to be important for schwannoma growth." (PMID 40794298, 2025). "However, when numerous schwannomas are discovered, they tend to be associated with NF2." (PMID 39618887, 2024). "The vast majority of schwannomas are solitary and sporadic, but they can also be associated with certain conditions, presenting as multiple schwannomas in diseases such as neurofibromatosis type 2 (NF2), schwannomatosis, Carney syndrome, and syndrome with nevi and vaginal leiomyomas." (PMID 39157066, 2024). "NF2 patients develop multiple tumors including bilateral vestibular schwannomas (VS), associated with possible bilateral hearing loss, tinnitus, and/or balance disturbances, as well as schwannomas on other cranial and spinal nerves, meningiomas and ependymomas." (PMID 38372904, 2024). "However, its use is currently reserved for patients with progressive NF2-associated schwannomas." (PMID 36672540, 2022). "Human schwannomas (SCHW) are associated with mutations or deregulated expression of NF2, a protein known to form a complex with WWC proteins, activating Hippo signaling." (PMID 33467643, 2021).